USP4 (ubiquitin specific peptidase 4)
Diseases named in the same sentence as USP4 in open-access papers (continued):
Sharing a sentence is not in itself a finding about the gene and the disease.
colitis (1 paper, 2019). Inflammation of the colon. "Meanwhile, we found that USP4−/− mice developed fewer tumors as compared with USP4+/+ mice using a colitis-associated colorectal tumorigenesis mouse model." (PMID 30514904, 2019).
colorectal tumor (1 paper, 2019). "Moreover, genetic deletion of USP4 or treatment with USP4 inhibitor, Vialinin A, inhibits colorectal tumor growth, implicating the potential clinical applications of USP4 inhibitors for future cancer therapy." (PMID 30514904, 2019).
depression (1 paper, 2023). "Another novel locus for smoking initiation has been linked with smoking-related phenotypes in previous studies: rs6778080 on USP4 was linked to the lifetime smoking index and depression." (PMID 37147289, 2023).
embryonic carcinoma (1 paper, 2016). "Based on linear changes in the relative abundances of the short and long isoforms observed during differentiation of P19 embryonic carcinoma cells (Gray, unpublished) we postulate that E7 of USP4 may be subject to regulated alternative splicing in therian mammals." (PMID 26833277, 2016).
endometrial cancer (1 paper, 2024). Primary or metastatic malignant neoplasm involving the endometrium (mucous membrane that lines the endometrial cavity). "USP4 alterations in breast, ovarian, cervical and endometrial cancers from 49 studies (18486 samples) were analyzed." (PMID 38734703, 2024).
endometriosis (1 paper, 2025). The growth of functional endometrial tissue in anatomic sites outside the uterine body. "In the ovary, (a tissue commonly affected by endometriosis) the prominent involvement of MFHAS1, CLDN23, USP4, and GATA4 was identified, all of which are regulated by eQTLs." (PMID 40863222, 2025).
epilepsy (1 paper, 2024). A brain disorder characterized by episodes of abnormally increased neuronal discharge resulting in transient episodes of sensory or motor neurological dysfunction, or psychic dysfunction. "Consequently, a downregulation of USP4 in epilepsy might thus even have detrimental instead of beneficial effects in mTLE." (PMID 37874479, 2024).
gynecologic cancers (1 paper, 2024). "The result showed that USP4 depletion and mutation were frequently observed in these gynecologic cancers." (PMID 38734703, 2024). "Furthermore, we identified several loss-of-function mutations of USP4 in human gynecological cancers, the catalytic activity of which or their interaction with BRCA1 is disrupted." (PMID 38734703, 2024).
Hyperglycemia (1 paper, 2023). An increased concentration of glucose in the blood. "USP22 in pancreatic β-cells, USP2 in adipose tissue macrophages, USP9X, 20, and 33 in myocytes, USP4, 7, 10, and 18 in hepatocytes, and USP2 in hypothalamus improve hyperglycemia, whereas USP19 in adipocytes, USP21 in myocytes, and USP2, 14, and 20 in hepatocytes promote hyperglycemia." (PMID 36834633, 2023).
invasive breast carcinoma (1 paper, 2024). A carcinoma that infiltrates the breast parenchyma. "Notably, USP4 protein level was correlated with tumor grade in patients with invasive breast cancer." (PMID 38734703, 2024).
liver disease (1 paper, 2021). "With the regulatory role of deubiquitination in inflammation reaction is highly valued, a key role for the deubiquitinase USP4 has been reported in some liver disease." (PMID 33295107, 2021). "However, the conclusion of the role of USP4 play in liver disease is converse." (PMID 33295107, 2021).
metastatic melanoma (1 paper, 2018). A melanoma that has spread from its primary site to another anatomic site. "In addition, USP4 expression in metastatic melanomas was significantly higher than that in primary ones." (PMID 29542252, 2018).
metastatic tumors (1 paper, 2018). "However, no metastatic tumors were found in the SK-Hep1-shRNA/USP4 cell group." (PMID 30335615, 2018).
non-alcoholic fatty liver disease (1 paper, 2023). "Moreover, the interaction of USP4 with TAK1 and the following TAK1 deubiquitination plays a key inhibitory role in non-alcoholic fatty liver disease (NAFLD)." (PMID 37304282, 2023).
non-small cell lung carcinoma (1 paper, 2020). A group of at least three distinct histological types of lung cancer, including non-small cell squamous cell carcinoma, adenocarcinoma, and large cell carcinoma. "We used shRNAs specific for USP4 to facilitate the knockdown of USP4 in human non-small cell lung cancer (NSCLC) H1975 and A549 cells." (PMID 32549341, 2020).
papillary thyroid carcinoma (1 paper, 2024). "However, the exact biological functions and underlying mechanisms of USP4 in the progression of papillary thyroid carcinoma (PTC) remain elusive." (PMID 39393052, 2024).
Peritoneal Fibrosis (1 paper, 2015). Disorder characterized by a wide range of structural changes in PERITONEUM, resulting from fibrogenic or inflammatory processes. "We demonstrated that Akt modulates TGF-β1-induced MMT and peritoneal fibrosis in PD via downstream interactive signaling molecules, such as, Smurf2 and Smad7, and USP4 and TβR-1." (PMID 25885904, 2015).
rheumatoid arthritis (1 paper, 2020). A chronic, systemic autoimmune disorder characterized by inflammation in the synovial membranes and articular surfaces. "For example, USP4 inhibition has been implicated in the treatment of rheumatoid arthritis." (PMID 33584299, 2020).
skin cutaneous melanoma (1 paper, 2018). "What's more, we turned to TCGA skin cutaneous melanoma (SKCM) database to analyse the status of USP4." (PMID 29542252, 2018).
Stroke (1 paper, 2025). Sudden impairment of blood flow to a part of the brain due to occlusion or rupture of an artery to the brain. "This discovery suggests that selective USP16/USP4 inhibitors may synergize with existing ROS scavengers to develop novel combinatorial therapeutic strategies for stroke." (PMID 40529211, 2025). "Importantly, pharmacological inhibition of USP4 activity enhances KEAP1 ubiquitination, triggering NRF2-dependent antioxidant responses and conferring robust neuroprotection in stroke models—evidenced by reduced neuronal apoptosis and improved functional recovery." (PMID 40529211, 2025).
thyroid cancer (1 paper, 2024). "Noticeably absent from the current literature is a thorough understanding of the biological roles and precise mechanisms underpinning USP4 in thyroid cancer progression." (PMID 39393052, 2024). "The intricate interplay between USP4 and thyroid cancer remains relatively unexplored, warranting focused investigations to elucidate its contributions to the pathogenesis of this specific malignancy." (PMID 39393052, 2024).
trichorhinophalangeal syndrome type I (1 paper, 2021). An autosomal dominant malformation syndrome caused by mutations in TRPS1 characterized by distinctive craniofacial and skeletal abnormalities. "Similarly, trichorhinophalangeal syndrome type I (TRPS1) functions as a scaffold protein involved in the USP4-induced stabilization of HDAC2 through bringing them together to form the TRPS1-USP4-HDAC2 complex." (PMID 33681193, 2021).
turban tumor syndrome (1 paper, 2011). "The cylindromatosis/turban tumor syndrome gene (CYLD) on chromosome 16 ranked highest, followed by acylaminoacyl-peptidase (APEH), dystroglycan (DAG1), macrophage-stimulating protein (MST1) and ubiquitin-specific peptidase 4 (USP4), all located on chromosome 3." (PMID 21931648, 2011).
uterus cancer (1 paper, 2019). "A TCGA UCEC project (uterus cancer) sample, A0UV, harbored a C > A missense variant (chr3:49316319) in exon 21 of the USP4 gene." (PMID 31631560, 2019).
viral infection (1 paper, 2018). "During viral infection (Sendai virus), USP4 has been found to remove K48-linked polyubiquitination chains from RIG-I and positively regulate the RIG-I-mediated antiviral response." (PMID 30194441, 2018).
cancer (57 papers, 2014 to 2026). A tumor composed of atypical neoplastic, often pleomorphic cells that invade other tissues. "Mounting evidence supports the assertion that USP4 serves as a promising biomarker and plays a pivotal role in diverse cellular and biological processes associated with various cancers." (PMID 39393052, 2024). "When its expression or activity is aberrant, USP4 is implicated in the progression of a wide range of pathologies, especially cancers." (PMID 33681193, 2021). "The deubiquitinating enzyme USP4 is associated with outcome in several carcinomas." (PMID 37308746, 2023). "USP4 deubiquitinates many well-known proteins (e.g., tumor suppressors such as pRb) associated with the key processes involved in both cellular homeostasis and diseases, especially cancer, where USP4 is frequently overexpressed." (PMID 34948102, 2021). "USP4 is now known to deubiquitinate many well-known target proteins associated with key processes involved in both cellular homeostasis and disease, especially cancer where USP4 is frequently dysregulated." (PMID 33681193, 2021). "This may be caused by the highly heterogeneity of cancers and the alternative deubiquitinating substrates for USP4." (PMID 31987030, 2020). "Therefore, combined with previous studies, our results highlighted that the biological role of USP4 in cancer development is not only associated with tumour type, but also highly dependent on the context of malignant characteristics." (PMID 29542252, 2018). "Additionally, USP4 is associated with outcome and progression of several cancers." (PMID 37308746, 2023). "This complexity suggests that the impact of USP4 on cancer pathogenesis is nuanced and dependent upon the intricate interplay within distinct cellular contexts." (PMID 39393052, 2024). "Simultaneously, accumulating evidence from both in vitro and in vivo studies suggests that elevated USP4 expression enhances the proliferative and migratory capabilities of cancer cells." (PMID 39393052, 2024). "ATAD2, BRMS1L, PUF60, SHQ1, and USP4 were found to influence overall survival in 15, 9, 13, 13, and 12 of the 21 cancer types, respectively." (PMID 39127727, 2024). "Although prior studies have elucidated the oncogenic roles of USP4 in various cancers, its function and molecular mechanisms in PTC remain largely unexplored." (PMID 39393052, 2024). "Since then, alterations in USP4 expression were found in several cancer entities including an upregulation in HNSCC." (PMID 37308746, 2023). "Ubiquitin-specific protease 4 (USP4) represents a potential oncogene involved in various human cancers." (PMID 37949874, 2023). "CYLD and SMPD2 were characteristics of G2 cancer, and TNFR1, TNFR2, NFKB1, TAB2, and USP4 for G3 cancer." (PMID 37233761, 2023). "Mounting evidence from in vitro and in vivo studies has indicated that USP4 has a crucial role in multiple cellular and biological processes, and USP4 overexpression enhances the proliferation and migration abilities of cancer cells." (PMID 37949874, 2023). "In recent years, USP4 has gained interest as an anticancer target, contributing to cancer cell proliferation and invasion." (PMID 36144645, 2022). "USP4 displays pathological roles in different types of cancers, mainly solid tumors, and several inflammatory diseases, such as asthma." (PMID 36144645, 2022). "For these reasons, selective inhibitors of USP4 have been actively searched, to provide research tools and drug candidates potentially useful to combat cancers and inflammatory diseases." (PMID 36144645, 2022).
cancer (continued). "For example, USP4 has been reported to be involved in regulation cell cycle, proliferation, and DNA repair and also participated in progression of various cancers, such as lung cancer, breast cancer, liver cancer, and colorectal cancer." (PMID 36582601, 2022). "On the other hand, quite a few studies discovered that USP4 exerts suppressive functions in particular types of cancer." (PMID 33681193, 2021). "Even if suitable inhibitors became available, the use of USP4 as a therapeutic target must be considered carefully as it plays a tumor-suppressing role in some types of cancer." (PMID 33681193, 2021). "USP1 function as an oncogene by interacting with DNA repair signal through PCNA and FANCD2, USP4 promote cancer progression by deubiquitinating TRAF2 and TRAF6 and thereby regulating the TGFβ signaling pathway." (PMID 34545063, 2021). "USP4 not only plays a role in promoting cancer in a variety of tumor tissues but also indicates a poor prognosis when highly expressed." (PMID 34179009, 2021). "USP4 has been suggested as a potential oncogene and is observed to be highly upregulated in several cancers." (PMID 32549302, 2020). "Like other USPs, previous basic experimental studies have unmasked the versatile roles of USP4 in numerous pathological and physiological processes, especially in cancers." (PMID 32669974, 2020). "The current study suggests that USP4 is a novel target mediating the tumorigenic effect of Snail1 by controlling the signaling for inflammation and stemness in cancer cells." (PMID 31936290, 2020). "USP4 is a potential cancer therapy target as it deubiquitinates and facilitates the nuclear localization of β-catenin, acting as a positive regulator of the Wnt/β-catenin pathway." (PMID 32549302, 2020). "The therapeutic and prognostic potential of USP4 in various cancers has been recently revealed in view of numerous regulated pivotal signaling pathways through its deubiquitination capacity." (PMID 32669974, 2020). "With the regulatory role of deubiquitination in tumorigenesis is high valued, a key role for the deubiquitinase USP4 has been reported in some cancers." (PMID 30335615, 2018). "Ubiquitin specific protease 4 (USP4) is a highly networked deubiquitinating enzyme with reported roles in cancer, innate immunity and RNA splicing." (PMID 26833277, 2016). "The critical function of USP4 in regulating pathways fundamental for cellular life is emerging, together with its involvement in cancer (notably its role in upregulating TGF-β response)." (PMID 25404403, 2014). "The fact that USP4 is highly expressed in various cancers indicated a critical role for USP4 in the tumor-promoting arm of the TGF-β/SMAD pathway." (PMID 24756567, 2014). "Survival analysis showed that several of the dysregulated genes (e.g. ATAD2, BRMS1L, PUF60, SHQ1, and USP4) have an impact on prognosis in multiple cancer types, thereby further highlighting the clinical significance of aberrant gene expression patterns on patient survival." (PMID 39127727, 2024). "The observed dual role of USP4 in cancer underscores its intricate involvement in diverse cellular pathways, which may be contingent upon cell type-specific variations." (PMID 39393052, 2024). "USP4 level was elevated in G1 and G3, while it was decreased in G2 cancer." (PMID 37233761, 2023). "USP4 may exert completely opposite effects in the same cancer, possibly because the roles of USP4 in cancer are controlled by a complex network of pathways that vary in different cell types." (PMID 37949874, 2023). "As aberrant alternative splicing is a critical cause of cancer development, we sought to find the genes regulated by USP15 and USP4, which may, in turn, affect the cancer progression phenotype." (PMID 35027535, 2022). "Therefore, examining the splicing regulation of the splicing factor SRSF1 by USP15 and USP4 in cancer progression was our particular interest." (PMID 35027535, 2022).
cancer (continued). "Therefore, abnormal expression of USP4 can either increase or decrease tumorigenesis depending on the cell context, suggesting a multidimensional role for USP4 in cancer." (PMID 33681193, 2021). "Based on these results, we speculated that the specific roles of USP4 in modulating cancer progression are complicated and diverse, which depend on tumor types and tumor microenvironment." (PMID 34335955, 2021). "However, later studies demonstrated that USP4 enhanced Wnt signaling through stabilizing and facilitating nuclear localization of β-catenin, especially in cancer." (PMID 33681193, 2021). "Thus, in addition to identifying more effective USP4 inhibitors targeting USP4, future research should also focus on understanding which cancers would likely benefit from this treatment along with other diseases where USP4 would inhibit progression." (PMID 33681193, 2021). "Therefore, aberrant USP4 has been explored in numerous cancers and related to either favorable or unfavorable prognosis of the patients." (PMID 32669974, 2020). "Indeed, knockdown of USP4 in the cancer cell lines D121, LLC, H1299, and HCC827 increased expression of the stemness genes Oct4, Sox2, Nanog, KLF4, ABCG2, and ALDH1 in different degree in different cell lines as measured by RT-qPCR." (PMID 31936290, 2020). "The biological function of USP4 in cancer development appears to be complex." (PMID 32549341, 2020). "USP4, one of the DUBs members which participates in deubiquitination, an inverse process of ubiquitination, can regulate various classical cancer-related signaling pathways, and thereby plays a vital role in some pathological and physiological processes including tumor initiation and progression." (PMID 32669974, 2020). "The DNA repairment capacity may make USP4 a tumor promoter in cancer progression which may be a potential target in tumor therapy." (PMID 32669974, 2020). "Database analysis revealed an inverse correlation between USP4 and IL-8 expression levels, suggesting that USP4 may negatively regulate inflammatory responses in cancer cells." (PMID 31936290, 2020). "In all cancer cell lines, knockdown of USP4 increased intrinsic activation of NF-κB." (PMID 31936290, 2020). "It was recently suggested that USP4 plays a key role in multiple malignant tumors." (PMID 33178601, 2020). "In addition, the USP4 gene was downregulated during enrichment of stemness in cancer cells as evidenced by the sphere forming assays." (PMID 31936290, 2020). "Therefore, anti-USP4 therapy can play a role in overturning immunosuppressive microenvironment of cancers." (PMID 32669974, 2020). "The functions of USP4 in regulation of cancer cell inflammatory status were then investigated." (PMID 31936290, 2020). "The main reason for the distinct roles of USP4 in cancers could be that USP4 has different partners in different tumor types." (PMID 30335615, 2018). "Interestingly, even in the same cancer and signaling pathway, USP4 presents opposite mediation mechanism and role." (PMID 30335615, 2018). "The same authors found that USP4 is overexpressed in several types of human cancer, and they suggest that USP4 could be a potential oncogene." (PMID 27516771, 2016). "Hence, restoring USP4 levels is important for suppressing cancer progression." (PMID 38715050, 2024). "Therefore, USP4 plays different roles in different types of cancer cells, and whether it promotes or suppresses cancer remains controversial." (PMID 36969062, 2023). "Moreover, the prognostic value of USP4 in cancers has also been confirmed." (PMID 36582601, 2022). "Moreover, USP4 can also act as a prognostic biomarker in several cancers." (PMID 32669974, 2020). "Thus, suppression of USP4 could increase cancer cell stemness both directly and indirectly through upregulated NF-κB activation." (PMID 31936290, 2020).